CD44 (CD44 molecule (IN blood group))
Diseases named in the same sentence as CD44 in open-access papers (continued):
Sharing a sentence is not in itself a finding about the gene and the disease.
tumor (continued). "Similar to the homeostatic conditions, CD11c:DTA mice showed reduced or enhanced fractions of CD4+CD44+ T cells and CD8+CD44+ T cells or CD8+CD62L− T cells in Spl as compared with WT mice under tumor-bearing conditions." (PMID 39206204, 2024). "This is consistent with literature that ADAM17 mediates the cleavage of CD44 extracellular domain (ectodomain) in various types of cells including tumor cells." (PMID 38177179, 2024). "One likely role for CD44 as a driver of tumor growth is as a cell receptor responding to extracellular cues relayed via the various ligands which bind CD44." (PMID 38539529, 2024). "For example, CD44-positive CSCs display an inverse relationship with CD8 + T-cell expression levels thereby favouring T-cell-induced tumour-killing inhibition." (PMID 38816670, 2024). "We observed an increase in ALDH1+/CD44+/BMI-1- tumour cells in metastatic lesions compared to primary tumours." (PMID 38719848, 2024). "AF1q expression was found in 178 (97.8%) tumor samples (p < 0.001) and CD44 expression in 64 (35.2%) tumor samples (p = n.s)." (PMID 38987552, 2024). "CD44, a commonly used tumor stem cell marker in EC, can self-renew and rebuild tumor tissues and is notably expressed in ESCCs with high TDO2 expression, indicating its potential role in tumor recurrence, metastasis, and drug resistance." (PMID 38462620, 2024). "Among the interaction molecular pairs, tumour invasion‐related pairs, including CD74_MIF, SPP1_CD44, were enriched among macrophages and MYH11+ CAFs." (PMID 39294858, 2024). "Many studies have demonstrated that CD44 serves as a marker for several tumor stem cells, including gastric CSCs 39-42." (PMID 38495505, 2024). "For instance, during skin injury, CD44-expressing mast cells elevate interleukin-10 expression (IL-10), which, in turn, activates fibroblasts to produce excessive HMWHA and diminish collagen deposition and inflammatory macrophage polarization." (PMID 39194478, 2024). "Deletion of Id2 resulted in a marginally decreased frequency of tumor-infiltrating central memory cells (CD44+CD62L+) among adoptive CD45.2+ OT-I CD8+ T cells from Id2fl/flCd4-Cre+ OT-I mice compared to those from Id2fl/flCd4-Cre− OT-I mice." (PMID 38287103, 2024). "Following extravasation, the internalization and transcytosis that are mediated by the tumor cell CD44 contribute to the penetration of the CS-coated NPs in tumor tissues." (PMID 38177179, 2024). "Noteworthy, different tumor types possess different stem cell makers; we thus selected the most common markers, CD44, SCA-1, CD166, and CD133, in our analyses." (PMID 38255301, 2024). "Because of the engagement of the anti-CD44 mAb, CD44–Doxil showed higher affinity for tumor tissue, with a higher T/NT ratio than Doxil alone." (PMID 38254219, 2024). "These biomarkers of epithelial mesenchymal transition and CD44 related to tumor stem cells were up-regulated." (PMID 38737444, 2024). "In NCDTs, increasing evidence indicates that CD44-high cells with stem-like properties contribute significantly to tumor heterogeneity and therapeutic resistance." (PMID 39518076, 2024). "There are also ongoing studies on tumor heterotransplant cell lines to demonstrate the ability of CD44+ to induce tumor formation in NOD/SCID mice." (PMID 39188680, 2024). "Hyaluronic acid is widely utilized as a kind of carrier for anti-tumor medications on account of excellent biocompatibility, biodegradability, and selectively binding to the CD44 molecule present on tumor cell surfaces." (PMID 39770059, 2024). "We also found that stemness‐related genes, e.g., CD44 and CD133, were overexpressed in L‐side tumor cells, and overexpression of CD44 brought a worse prognosis in the FDU‐ICC cohort." (PMID 39716897, 2024). "HUVECs cultured in the presence of growth factors express a relatively high level of CD44 and have been used to model tumor ECs." (PMID 38177179, 2024).
tumor (continued). "PLTs specifically bind to hyaluronic acid receptors (CD44) expressed on tumor cells through surface P-selectin, enabling them to target damaged areas and penetrate tumors for therapeutic effect." (PMID 39065602, 2024). "Lastly, we isolated the CSC subpopulation from freshly isolated patient primary PDAC tumours by using FACS-sorting of triple positive CD133+/CD44+/SSEA4+ cells and treated these with GCN5 inhibitors for 5 days followed by measuring live cell numbers." (PMID 38678032, 2024). "Flow cytometry analysis revealed a significant decrease in the proportion of CD44+ positive cells in GC cell lines and tumor spheres in the Circ-0075305 overexpression group compared to that in the control group." (PMID 38714724, 2024). "The aim of our study was to examine the expression of CD44 in different subtypes of TGCTs and tumor cell lines and to investigate the possible correlation of CD44 expression with the malignant behavior of the tumors." (PMID 38796656, 2024). "Several targets showed specifically higher expression in HET cases, including TIM3, BCL2, S100B, and CD44 (tumor ROI only), implying a more immunosuppressive microenvironment within these tumors." (PMID 38300710, 2024). "CD44 can therefore be used to isolate or enrich CSCs through fluorescence-activated sorting of patient cells, tumor tissue heterotransplantation, or cell culture." (PMID 39188680, 2024). "RG7356-binding CD44+ tumor cells stimulated the secretion of chemoattractants and facilitated the recruitment of immune cells, such as macrophages, leading to antibody-dependent cellular phagocytosis of cancer cells by macrophages." (PMID 38672650, 2024). "Numerous reports have been published on CD44-mediated tumor targeting using hyaluronic acid (HA) or CS-decorated NPs." (PMID 38177179, 2024). "Hyaluronic acid is recognized by a plethora of different receptors, with particular interest in Cluster of Differentiation 44 (CD44), although the majority of them are overexpressed in tumor tissues." (PMID 38791253, 2024). "It has been demonstrated that the enhanced expression of basigin triggers the formation of a lipid raft-associated supramolecular complex basigin–CD44–EGFR, which appears to favor the invasive properties of tumor cells." (PMID 39195201, 2024). "The nature of specific binding between HA/HA derivatives and CD44 provides targeted delivery for antitumor drugs to tumor cells." (PMID 38318188, 2024). "The endothelial cells in this study (UV2) expressed CD44, the same as tumor blood vessels, HARE, and internalized HA." (PMID 39273689, 2024). "In particular, gastric carcinoma is a heterogeneous tumor comprising clusters of chemoresistant cancer stem cells (CSCs), with subpopulations expressing elevated CD44 and high ALDH activity." (PMID 38544822, 2024). "Our data suggest that accumulation of the NPs at tumor site is largely achieved through targeting of CD44 on tumor ECs." (PMID 38177179, 2024). "MIF, CD74, and CD44 exhibit interplay and mutual regulation mechanisms in tumor development and progression." (PMID 38277205, 2024). "As a result, CD44 was closely related to tumor-promoting biological processes, such as metastasis, angiogenesis and epithelial-mesenchymal transition (EMT) of AML, LUAD, and RCC." (PMID 38590654, 2024). "In this nanoplatform, CS confers tumor‐targeted and subsequently pH‐responsive drug delivery behavior by binding to glycoprotein CD44, leading to the release of P780 and KET." (PMID 38308137, 2024). "Stearylamine (SA) was utilized to develop cationic nanovesicles to orient the nanovesicles to the tumor externalized phosphatidylserine, while hyaluronic acid (HA) was used to develop CD-44 targeting nanovesicles." (PMID 37644299, 2024). "Our study found that in HNSCC, SHMT2 suppresses anti-tumor immune responses by down-regulating CD44 expression and inhibiting T cell activation through MIF." (PMID 38625586, 2024).
tumor (continued). "Second way is to inhibit tumor development and progression by disrupting the connection between CD44-HA." (PMID 39026213, 2024). "CD44 is heavily expressed in many types of tumors and is apparently involved in tumor aggressiveness and metastatic potential." (PMID 38942020, 2024). "RFX1 reduces the expression of multiple genes that are oncogenic or enhance tumour growth, such as c‐Myc, transforming growth factor‐β2 and CD44." (PMID 39636301, 2024). "CD44 is a cell surface glycoprotein that is expressed in many cell types, such as lymphocytes, fibroblasts, smooth muscle cells, and tumor cells." (PMID 38802835, 2024). "In vivo, the combination therapy induced more proliferative KLRG1‐high PD1‐low CD8+ T‐cells and activated CD103+ DC in the tumor site and increased tumor‐specific CD44+ CD8+ T‐cells in the lymph node." (PMID 38400597, 2024). "CD44, a cell surface glycoprotein, plays a crucial role in tumor cell adhesion, migration, and survival." (PMID 39010066, 2024). "Conversely, ectopic PCAT6 overexpression markedly increased tumor incidence and CD44+ breast CSCs, c‐Myc, and Ki67 expression in xenografts." (PMID 38626369, 2024). "Higher expression of CCND1 and CD44 in p16-/HPV- tumours relative to p16+/HPV+ aligns with their poorer prognosis." (PMID 39328208, 2024). "CD44 is a well-known marker of tumour stem cells and a key regulator of the EMT, which is involved in tumorigenesis, progression, and metastasis." (PMID 38546403, 2024). "Our results indicate that the increased expression of CD44 mRNA and protein correlate positively with worse clinical outcomes, as this is denoted through the analysis of tumor size, Furhman grade, and overall survival." (PMID 38790166, 2024). "CD44 is a receptor that plays a crucial role in tumor cell proliferation, invasion, and lymph node metastasis." (PMID 39513925, 2024). "When expressed by tumor cells, CD44 has constitutive activity, displaying the strongest HA binding ability." (PMID 38903499, 2024). "Our findings indicate that in EC patients having undergone NRCHT+R, the overall expression of FAK, HIF-1α, Ki67, and CD44 was higher in tumor nests, whereas ILK was higher in tumor stroma." (PMID 38727811, 2024). "Hyaluronic acid (HA) has attracted much attention in tumor-targeted drug delivery due to its ability to specifically bind to the CD44 cellular receptor, which is widely expressed on cancer cells." (PMID 38541384, 2024). "Membranous or cytoplasmic CD44 staining was observed in ductal and myoepithelial cells, while tumor cells of most studied P(LG)A cases also expressed ALDH1 and CD166." (PMID 39858584, 2024). "The induced expression of CD44 in the paranecrotic area of HT‐29 control xenograft tumors (compared to tumor margin) indicates a functional link between CD44 and tumor hypoxia response." (PMID 37849446, 2024). "In this nanoplatform, CS confers tumor‐targeting and subsequently pH‐responsive drug delivery behavior by binding to glycoprotein CD44, thus releasing P780 and KET." (PMID 38308137, 2024). "Cell matrix interactions mediated by CD44 have been shown to activate tumorigenic signaling and drive tumor progression through diverse molecular mechanisms." (PMID 38796656, 2024). "Concordantly with the cancerous up‐regulation of CD44 isoform 3 (the most highly expressed isoform), total CD44 levels were also increased in tumor samples." (PMID 37849446, 2024). "Pan‐CD44 knockdown (kd) independently impaired primary tumor formation and abrogated distant metastasis in CRC xenografts." (PMID 37849446, 2024). "In the CD24−/CD44+‐breast CSCs xenotransplanted group treated with a high dose of doxorubicin, the tumor mass in the subcutaneous region was completely necrosed and replaced with fibrous tissue." (PMID 38522013, 2024). "CD44 is frequently expressed in high levels in tumor cells and is considered as a cancer stem cell marker." (PMID 38796656, 2024).
tumor (continued). "The CD44/HA interaction has been widely investigated for the development of tumor-targeting delivery systems since the CD44 receptor is overexpressed in many cancers." (PMID 39458615, 2024). "C002 treatment also increased the tumor infiltration of CD44(+)CD4(+) T cells, suggesting a shift from naïve to effector/effector memory T cell populations." (PMID 38895115, 2024). "Our results revealed that the most substantial increase in CD-44 expression occurs precisely in the tumour cell line when exposed to its rigidified microenvironment, coupled with an increase in cellular spreading area." (PMID 38172135, 2024). "Due to its role in signal transduction, CD44 participates in normal cellular functions as well as tumor biological behaviors, including proliferation, differentiation, invasion, and motility." (PMID 37849446, 2024). "CD44 can be utilized as a marker for tumor stem cells, and it has been demonstrated that increased infiltration of TAMs is correlated with upregulation of CD44 expression and the generation of tumor stem cells." (PMID 39169402, 2024). "The presence of CD44 in tumor stroma of TGCTs is also correlated with neovascularization in tumor microenvironment." (PMID 38796656, 2024). "Previous studies uncovered that CD44 participated in the modulation of energy metabolism in tumor cells." (PMID 38287411, 2024). "Immunosuppression heightens the likelihood and severity of HNC, with lactic acid-induced immunosuppression mediated by GPNMB and CD44 in the tumor microenvironment contributing to cancer progression." (PMID 39040446, 2024). "To test the effect of Sfrp1 on tumor tissues, we determined the percentage of CD44+ CD133+ tumor cells in Sfrp1 KO and WT mice." (PMID 38625488, 2024). "Flow cytometry was used to collect GFP+ CD44+ CCs 14 d after tumor cell transplantation, and qRT-PCR was used to examine the expression of CSC markers (Oct4, Abcg2, Sox2, Bmi1, and Ssea1)." (PMID 38625488, 2024). "Immortal, non-malignant MCF12A mammary epithelial cells expressing p27CK-DD acquire expression of CSC markers, CD44+ CD24low/-, and the ability to form tumor spheres and colonies in soft agar." (PMID 38886396, 2024). "Both in vitro and in vivo experiments showed significant antitumor effects, and C26 tumor-bearing mice treated with CD44-Doxil presented with longer survival times." (PMID 38254219, 2024). "The stemness of tumor cells can be assessed using multiple methods, such as expression of CD44, MET, OCT4 etc.." (PMID 38600440, 2024). "This protein family has a similar ectodomain architecture to that of CD44 and is involved in several cell processes including angiogenesis, inflammation, tumor development and cell adhesion." (PMID 38254353, 2024). "A significant increase in human CD44 mRNA expression levels was observed in tumor tissues of mice xenotransplanted with CD24−/CD44+‐breast CSCs as compared to sham control." (PMID 38522013, 2024). "Once again, B7-H4 was more frequently coexpressed with EpCAM on tumor cells compared to CD44 on tumor cells." (PMID 38687247, 2024). "Significantly enhanced phototoxicity toward CD44-overexpressing A549 cells was observed in both the 2D monolayer cell culture and 3D tumor spheroids." (PMID 38675130, 2024). "It is important to note that expression of CD44 is elevated in tumor-macrophages, which we theorize in cancer are highjacked by pathogens." (PMID 39981299, 2024). "The activated (CD44+CD62L−) Tregs were the initially dominant Treg population in the dLN of tumor-bearing mice." (PMID 38932362, 2024). "While CD44 immunostaining was increased at metastatic sites, it was notably significantly higher than that observed in central regions of primary tumours (p = 0.0463)." (PMID 38719848, 2024). "Although the data are conflicting, studies have shown that increased CD44 expression strongly correlates with higher histological tumor grade, advanced clinical tumor stage, shorter survival, and poor prognosis." (PMID 38672650, 2024).
tumor (continued). "In contrast, CD11c:DTA mice had a higher proportion of CD4+CD44+CD62L− T cells in tumor tissues than WT mice." (PMID 39206204, 2024). "In Papadopoulou's study, the increase in MMP1 and MMP13 expression followed by the decreased expression levels of CD44 was found to promote tumor growth." (PMID 38783892, 2024). "CD44 knockout animals have shown impacts on lymphocyte circulation and CD44 knockout tumor cells have significantly decreased proliferation, survival in vitro, and a slowed tumor development when implanted into mice." (PMID 39201626, 2024). "Cells expressing CD133 and CD44 markers have been shown to possess several characteristics that promote tumor growth and progression, including enhanced spheroid-forming ability and chemoresistance." (PMID 38672078, 2024). "Numerous studies confirmed the crucial role of high CD44 expression in the development of cancer, tumor growth, differentiation, and metastasis in CRC." (PMID 38672650, 2024). "By interacting with signaling molecules like c-Src, CD44 influences cell signaling pathways, promoting self-renewal and differentiation of tumor stem cells, thereby contributing significantly to tumorigenesis and progression." (PMID 39184916, 2024). "CD44 is a cancer stem cell marker and indicative of PCa tumour initiation, drug resistance, metastasis, and recurrence." (PMID 39336161, 2024). "We found that tumour cell-derived SRGN increased KDM5B expression in CAFs via interacting with its receptor CD44." (PMID 38862740, 2024). "LMW or oligo-HA is more prominently present in the periphery of the tumor cells and often correlates with a higher expression of CD44." (PMID 38543448, 2024). "Most studies seem to suggest a mechanism that involves EPR followed by targeting to CD44 on tumor cells." (PMID 38177179, 2024). "We performed histochemical staining of the spleens of tumor-ablated mice and observed that the combination treatment resulted in increased CD44 expression in mouse spleens." (PMID 38175694, 2024). "It was observed both the reduction and disaggregation of tumor spheroids when α-MG-loaded NPs conjugated to the CD44 thioaptamer were used, indicating an enhanced efficacy of this aptamer-modified approach." (PMID 38675202, 2024). "We first analyzed HA synthases HAS1, HAS2, and HAS3, hyaluronidases HYAL1 and HYAL2, ABCC5 transporter, and CD44 expression in tumor tissue (TT) in TCGA database." (PMID 39039104, 2024). "The plasma membrane protein CD44 (CD44 molecule (IN blood group)), which functions as a cell-cell and cell-stromal adhesion protein and is frequently overexpressed in tumor cells, is a marker of poor survival in the majority of solid tumors." (PMID 39463763, 2024). "The expression of CD44 isoforms can be correlated with tumor subtypes and also be a marker of cancer stem cells." (PMID 39840036, 2024). "Significantly, in a LL/2 tumor model, just one round of CD44- and CD25-targeted NIR-PIT achieved complete remission in 33% of the mice tested." (PMID 38612911, 2024). "In a study related to head and neck squamous cell cancer, CD44+ TCs contained pro‐angiogenic factors and stimulated tumor angiogenesis in comparison to CD44‐ TCs, which fully supports our observation of decreased VEGF release by CD44 kd spheres in normoxia." (PMID 37849446, 2024). "CD4+ T cells and CD8+ T cells displayed an enhanced expression of CD44 in TdLNs and Spl in WT mice during tumor progression." (PMID 39206204, 2024). "Modified tumor ECM interacts through multiple receptors, including CD44, on the cell surface of both tumor and stromal cells permitting intracellular signals that regulate cell responses and phenotype." (PMID 38796656, 2024). "The combination of PTX and CD44 siRNA delivered by the nanocarrier led to almost complete tumour shrinkage." (PMID 39125873, 2024). "CD44 and CD24 are commonly used markers for BCSCs, with CD44+/CD24‒ cells representing a stronger tumour stemness." (PMID 38725048, 2024).